WT1 (WT1 transcription factor)
Diseases named in the same sentence as WT1 in open-access papers (continued):
Sharing a sentence is not in itself a finding about the gene and the disease.
Wilms tumor (continued). "WT1 acts as an oncogene in Wilms' tumor (or nephroblastoma), gliomas and various other human cancers." (PMID 19737418, 2009). "Finally, WAGR syndrome (OMIM 194072), which includes Wilms’ tumor, aniridia, genitourinary anomalies, and mental retardation, is caused by either microscopic or submicroscopic deletion of chromosome 11p13-p12 in a region containing both the Wilms tumor 1, WT1 gene and the PAX6 genes." (PMID 19862335, 2009). "A similar analysis for WT1 confirms the role of WT1 in migration and Wnt signaling and suggests many new roles for WT1 in development, the nervous system, and in the progression of Wilms' tumor." (PMID 18564415, 2008). "Although WT1 was first identified as a tumor-suppressant gene of Wilms' tumor, subsequent studies revealed that WT1 is also essential for embryonic development, especially the kidney and gonads." (PMID 18445271, 2008). "Expression of WT1 has been observed in different types of solid cancers, such as ovarian cancer, mesothlioma of the lung, melanoma, breast cancer, as well as in Wilms’ tumor." (PMID 19662212, 2007). "The WT1 gene was originally identified as a tumor suppressor gene responsible for Wilms’ tumor, a kidney neoplasm of childhood." (PMID 19455234, 2007). "The prognostic value of WT1 gene expression was corroborated by later studies in patients with acute leukemia, nephroblastoma and breast cancer." (PMID 16606472, 2006). "Wilms' tumor is a kidney malignancy of childhood that is thought to arise as a result of inactivation of both alles of the Wilms' tumor gene (WT1) located at chromosome 11p13." (PMID 16606472, 2006). "A highly significant correlation has been found between WT1 mutation and CTNNB1 mutation in Wilms' tumours." (PMID 16909133, 2006). "WT1 was originally found to be a suppressor of Wilms tumour, as individuals with inactivated WT1 developed the Wilms tumour condition." (PMID 16281973, 2005). "Today, however, there are no specific recommendations for children with WT1 pathogenic variants in favor of bilateral prophylactic nephrectomy, and more recently, kidney-sparing surgery is recommended in cases of unilateral Wilms’ tumor." (PMID 40332152, 2025). "WTs and DSRCTs share the involvement of the Wilms tumor gene, WT1, in their pathogenesis." (PMID 40149257, 2025). "After a complex diagnostic process, it was discovered to be an adult WT1-negative Wilms tumour with blastemal predominance." (PMID 40177273, 2025). "Data from mouse models, human iPSC-derived organoids, and a recent analysis of bilateral Wilms’ tumors (also often WT1-mutant;) all support an earlier stage of origin of the tumors than other cases, for instance, before or at the stage where the intermediate and paraxial mesoderm separate." (PMID 38674106, 2024). ",23, 24, 25 This was also confirmed by long-term follow-up studies of patients with Wilms tumor and underlying WT1 variants, WAGR, or urogenital malformations (as a proxy for possible WT1 involvement), varying from 36% to 90% depending on the type or location of the variant." (PMID 39698353, 2024). "However, further research determined that while WT1 protein hyperexpression is evident in approximately 90% of nephroblastomas, only about 15% of these tumors present actual WT1 gene mutations." (PMID 38929778, 2024). "It should be noted, however, that WT1-mutant cases are favorable histology Wilms’ tumors, not high-risk cases as described in the present study." (PMID 38674106, 2024). "In children’s kidney tumors called Wilms tumors, WT1 is rendered inactive." (PMID 38352075, 2024).
Wilms tumor (continued). "It was hypothesized that Japanese Wilms tumors may be characterized by a higher incidence of WT1 deletion, which could contribute to the lower incidence of Wilms tumors in Japanese children as compared to Caucasian populations." (PMID 39272909, 2024). "In a Japanese study on unilateral Wilms tumors, the majority of Wilms tumors with WT1 anomalies showed stromal predominance, while the majority of Wilms tumors without WT1 mutations showed blastemal-predominant histology." (PMID 39272909, 2024). "Markers such as WT1, which is typically positive in Wilms’ tumor (in addition to PAX8, CD56, and CD57), help confirm a nephroblastic origin, while others like cytokeratins, desmin, and S-100 protein assist in identifying the specific tissue types within a tumor." (PMID 39596492, 2024). "Developmental syndromes such as WAGR (Wilms’ tumor, aniridia, genital anomalies and retardation) and DDS (Denys–Drash syndrome) are associated with WT1 pathogenic variations and were shown to have an increased risk of WT development (30–75%) and lower mean ages of WT diagnosis." (PMID 39593106, 2024). "All precursor lesions associated with Wilms tumor were positive for WT1, while those associated with pRCT and MTSCC were negative." (PMID 38260844, 2023). "Moreover, we identified hypermethylated DMCs at the WT1 locus, which are required for the normal formation of the genitourinary system and responsible for the formation of Wilms tumors, a renal tumor in children." (PMID 38093359, 2023). "WT1 is a transcription factor essential for the development of kidneys and gonads and has historically been known to be responsible for the tumorigenesis of Wilms' tumor, a rare renal tumor in humans." (PMID 38026668, 2023). "WT1 gene is muted in Denys–Drash syndrome (Wilms’ tumor, gonadal dysgenesis, nephropathy)." (PMID 37176098, 2023). "We have isolated and described thirteen cell lines from patients with WT1 mutant Wilms tumors." (PMID 36689432, 2023). "Although IHC expression of WT1 is usually undetectable in renal epithelial structures originating from the metanephric mesenchyme, i.e., proximal/distal tubules, WT1 transcripts have been documented in tubular structures within nephroblastomas." (PMID 35453662, 2022). "The Wilms tumor 1 (WT1) gene was discovered as a tumor suppressor gene in Wilms tumor." (PMID 35387670, 2022). "Wilms’ tumor 1 (WT1) have been primarily considered in the development of Wilms’ tumor." (PMID 35243014, 2022). "WT1 c.1387C>T has been reported in several patients with Wilms’ tumor." (PMID 34845858, 2022). "Most commonly, alterations in the WT1 gene have been observed in children with Wilms tumor and associated congenital anomalies, although cases are also known where Wilms tumor, as in our girls, is not accompanied by any congenital anomalies." (PMID 35205416, 2022). "A heterozygous nonsense WT1 mutant is associated with non‐syndromic POI and Wilms’ tumor." (PMID 34845858, 2022). "As to the son, the renal cells might receive a second hit in its remaining functional copy of WT1, leading to the development of Wilms’ tumor." (PMID 34845858, 2022). "WT1 was first identified as a tumor suppressor in nephroblastoma, while late studies revealed that it also acts as an oncogene in leukemia, indicating that it may regulate cell proliferation and invasion in a cell type-dependent manner." (PMID 36550096, 2022). "Although previous studies have reported the inhibitory effect of WT1 in Wilms' tumor, its role in renal cancer remains unclear." (PMID 35915803, 2022). "A rare heterozygous nonsense WT1 mutant is associated with non‐syndromic POI and Wilms’ tumor." (PMID 34845858, 2022). "Solid pRCC will be positive for CK7 and AMACR, but negative for WT1 and CD57, while, conversely, metanephric adenoma is only positive for WT1 and CD57, whereas Wilms’ tumor expresses only nuclear immunoreactivity for WT1 and, rarely, isolated cells with CK7 cytoplasmic positivity." (PMID 35453662, 2022).
Wilms tumor (continued). "Patients with several congenital anomalies such as WAGR syndrome (Wilms’ tumour, aniridia, genitourinary abnormalities, intellectual disability, WT1 gene), Denys-Drash syndrome, Beckwith-Wiedermann syndrome or isolated hemihypertrophy are at higher risk of developing WT." (PMID 36010142, 2022). "The constitutional WT1 pathogenic variant spectrum overlaps with those described here and in other studies of children who present with Wilms tumour rather than nephrotic syndrome." (PMID 34608521, 2022). "Therefore, although the presence of nephroblastoma and/or gonadal cancer in SRNS cases strongly suggests that WT1 pathogenic variants are involved in the pathogenesis of the disease, the exact molecular mechanism remains to be elucidated." (PMID 35610319, 2022). "Conversely, nephroblastomas apparently manifest most of the elements found in the normal embryonic kidney, but in a disorganized state; however, in contrast to their normal counterparts, the tubular epithelial-like structures in nephroblastomas frequently express WT1 transcripts." (PMID 35453662, 2022). "The Wilms’ tumor 1 (WT1) gene, mapping to chromosome 11p13, was initially described in 1990 as being a likely predisposing gene for nephroblastoma (Wilms’ tumor), a pediatric kidney cancer affecting 1 in 10,000 children and an archetypal model for tumorigenesis resulting from development gone awry." (PMID 35453662, 2022). "The causes for Wilms tumors are not precisely known, but gene alterations of WT1, CTNNB1, and WTX have been found in about 30%." (PMID 34073340, 2021). "WT1 was firstly identified as a tumor suppressor gene in nephroblastoma." (PMID 34513664, 2021). "WT1 is a tumor suppressor gene encoding a transcription factor (WT1) that generally represses gene expression and was first noted for its deletion in Wilms’ tumor." (PMID 34869013, 2021). "Taken together, in this WT1 mutant Wilms tumor no other clear pathogenic mutations except for WT1 and CTNNB1 are found." (PMID 33379206, 2020). "Much remains to be elucidated about the molecular basis of the WT1 mutant Wilms tumor subtype." (PMID 33379206, 2020). "It seems likely that an efficacious therapy for this subtype of WT1 mutant Wilms tumor might need a combination of drugs targeting these receptors or downstream signaling cascades." (PMID 33379206, 2020). "The WT1 variant is confirmed to be pathogenic for Denys-Drash syndrome (DDS), a rare disorder characterized by early-onset nephrotic syndrome and renal failure, pseudo-hermaphroditism, and a high risk of Wilms' tumor." (PMID 33392118, 2020). "Using the here described cell culture models of WT1 mutant Wilms tumors it can now be tested which of the receptors are crucial/essential for cell growth and whether targeting can result in growth arrest or apoptosis." (PMID 33379206, 2020). "Genetic defects in WT1 are associated both with isolated nephrotic syndrome (NPHS4) and syndromic NS with disorders of sexual development and nephroblastoma or gonadoblastoma (Denys–Drash syndrome, Frasier syndrome) and a wider array of developmental defects (Meacham syndrome)." (PMID 32843431, 2020). "While the absence of one copy of PAX6 and WT1 is established as the cause for aniridia and Wilms tumour (and genitourinary anomalies), respectively, the genetic causes that are behind the neurodevelopmental defects are less clear." (PMID 31861090, 2019). "WT1 was identified via homozygous intragenic deletions in isolated Wilms tumours cases." (PMID 30242502, 2019). "Wilms Tumor 1 (WT1) is a tumor suppressor gene involved in the etiology of Wilms’ tumor." (PMID 31223481, 2019). "In addition, these Wilms tumor‐derived cell lines with mutant WT1 genes are a valuable tool to identify less toxic agents that can induce more efficiently terminal skeletal muscle cell differentiation." (PMID 29542868, 2018).
Wilms tumor (continued). "WT-1 was initially discovered as a tumor suppressor in Wilms’ tumor, and is expressed in most serous adenocarcinomas of the ovary and peritoneum and mesotheliomas, as well as in Wilms’ tumors." (PMID 29433539, 2018). "Wilms tumors (WT) with WT1 mutations do not respond well to preoperative chemotherapy by volume reduction, suggesting resistance to chemotherapy." (PMID 29542868, 2018). "Although previously it was postulated that chemotherapy induces a more differentiated skeletal muscle phenotype in certain Wilms tumors, a direct comparison of WT1‐mutant Wilms tumor samples before and after chemotherapy using whole transcriptome analysis has not been reported." (PMID 29542868, 2018). "More recently, other work has shown that DNA methyltransferase 3A (DNMT3A) is a direct transcriptional target of WT1, suggesting that DNA methylation may be partly regulated by WT1 in Wilms' tumor cells." (PMID 30459215, 2018). "The Wilms’ tumor gene WT1 locates at the rightmost (the highest) peak on chromosome 11; it is a tumor-suppressor gene that encodes a zinc finger transcription factor regulating transcription of growth factors such as PDGF-A, growth factor receptor (IGF-IR) and other genes (RAR-α, c-myc and bcl-2)." (PMID 29073141, 2017). "In nephroblastomas, WT1 is nuclear and correlates with tumor histology." (PMID 28845162, 2017). "In this case, the tumor was established by orthotopically injecting Wilms tumor cells with elevated IGF1R signaling but without a WT1 mutation in the kidney of mice." (PMID 27213811, 2016). "The cytokine-initiated repression was reversible, observed on both basal and inducible expression, independent of Wilms’ tumor suppressor WT1 and caused in part via activation of the phosphatidylinositol-3-kinase/Akt pathway." (PMID 26566632, 2016). "Microdissection of ILNRs in WT1 mutant Wilms tumors revealed that these carry biallelic WT1 mutations but no CTNNB1 mutations, whereas the associated tumor cells had CTNNB1 mutations." (PMID 27213811, 2016). "Wilms tumor 1 gene (WT1) is a tumor suppressor gene originally identified in nephroblastoma." (PMID 27014421, 2016). "WT1 was first identified as a tumor suppressor gene in Wilms' tumor." (PMID 26573232, 2016). "Thus our immortalized cell line (imWilms10) represents the first cell culture model system for Wilms tumors with deleted WT1 genes." (PMID 27213811, 2016). "We have developed the pMHC array to detect CD8+ T-cell populations in leukaemia patients that recognise epitopes within viral antigens (cytomegalovirus (CMV) and influenza (Flu)) and leukaemia antigens (including Per Arnt Sim domain 1 (PASD1), MelanA, Wilms’ Tumour (WT1) and tyrosinase)." (PMID 26492414, 2015). "Interestingly, expression of WT1 is tightly regulated during development of the kidney (the organ in which Wilms’ tumor arises) and during hematopoiesis." (PMID 25794157, 2015). "This comparison showed a close resemblance between the Nes-Cre Wt1co mutants and the WT1-mutant tumours, especially with respect to the ectopic muscle development signature, whereas the phenotype in the Pax8+/CreWt1co mutant kidneys more resembled the one found in WT1-wild-type Wilms' tumours." (PMID 26035382, 2015). "Renin positivity may also be observed in some cases of Wilms’ tumor (WT-1 staining), renal cell carcinoma (RCC), or renal oncocytoma." (PMID 25177679, 2014). "In summary, renal tumors developing in Wt1-Igf2 mice carry the same alterations that occur in human tumors, thus recapitulating the process of development and progression of Wilms tumor in human patients and providing a highly relevant model for testing new molecular targeted therapies." (PMID 22875335, 2013). "Previous reported missense, nonsense or frame-shift mutations in WT1 hot spots in leukaemia or in Wilms’ tumour were not identified in the present study." (PMID 23484026, 2013).
Wilms tumor (continued). "Delayed 18F-FDG PET (3-h post 18F-FDG administration) and dual-contrast CT (intravenous and intraperitoneal contrast) provided a more accurate anatomic and metabolic characterization of Wilms tumors in Wt1-Igf2 mice during early development and progression of renal tumors." (PMID 22875335, 2013). "In 1990, WT1 was first described as a tumour suppressor gene in Wilms’ tumour." (PMID 23484026, 2013). "This frequency is comparable to that of known Wilms tumor suppressors WT1 and CTNNB1." (PMID 21080955, 2010). "In addition, WAGR syndrome (Wilms tumor, Aniridia, Genitourinary anomalies, and mental Retardation) is associated with a contiguous gene deletion which includes PAX6 and the WT1 gene (WT1)." (PMID 20806047, 2010). "The regulatory-network for WT1 targets in genomic regions relevant to Wilms' tumor is provided." (PMID 18564415, 2008). "We speculate that Wilms' tumor development is mediated by chromosomal rearrangements in the location of WT1 targets." (PMID 18564415, 2008). "WT1 is a tumor suppressor gene responsible for Wilms' tumor." (PMID 16606472, 2006). "In addition, the Wilm's Tumor suppressor (WT1) gene, which when lost in Wilm's tumors can result in activation of β-catenin, was downregulated 8-fold in HEK-TERST cells." (PMID 16522205, 2006). "The small number of WT1 mutations in Wilms' tumours suggests that WT1 can be inactivated by alterations that would not be detected by mutational analysis." (PMID 16909133, 2006). "Additionally, Wilm's tumor was demonstrated to present a high percentage of cases with nuclear WT1 staining; for this reason, correlation with clinical findings is necessary to do a differential diagnosis between Wilm's tumour and DSCRT in effusions." (PMID 15777480, 2005). "Similarly, WT1 typically suppresses IGF2 transcription; thus, WT1 mutations or functional loss led to increased expression of both IGF2 and miR-483, prominently observed in Wilms tumors." (PMID 41463366, 2025). "In addition, since the national centralization of pediatric renal cancer care at the end of 2014, more children with Wilms tumor (who often have truncating variants in the non-hotspot domain of the gene) were tested for WT1 aberrations." (PMID 39698353, 2024). "We assume that previously, truncating germline WT1 pathogenic variants may have been missed, particularly in (46,XX) patients with Wilms tumor without additional WT1-characteristic features." (PMID 39698353, 2024). "Awareness of an underlying WT1 variant is especially important in young females with Wilms tumor, because they often present without additional recognizable phenotype, but may still develop CKD resulting in kidney failure in the future." (PMID 39698353, 2024). "Studies have implicated population differences in the incidence of WT1 mutations, loss of imprinting of the IGF2 locus, and loss of heterozygosity of 1p/16q, or 1q gain as possible bases for epidemiological differences in the disease profile of Wilms tumors in various ethnic groups." (PMID 39272909, 2024). "Five patients (4 with a missense and 1 with a splice-site WT1 variant) underwent bilateral nephrectomies at ages < 7 years, due to untreatable kidney disease with hypertension and could therefore not develop Wilms tumors." (PMID 39698353, 2024). "However, in other Wilms’ tumors, wt1 is expressed normally, sometimes even more." (PMID 36412640, 2022). "Precisely because Wilms’ tumor rarely occurs in adults, with only 3% of cases being reported in patients >16 years old, it is frequently misdiagnosed as metanephric adenoma, since both entities are positive for WT1, with serious implications regarding prognosis and therapeutic strategy." (PMID 35453662, 2022). "Wilms tumor cells are notoriously difficult to establish as immortalized cell cultures and 2D cultures may more efficiently capture epithelial cells rather than blastemal cells that are characterized by high expression of WT1." (PMID 35406427, 2022).